LEP (leptin)
Diseases named in the same sentence as LEP in open-access papers (continued):
Sharing a sentence is not in itself a finding about the gene and the disease.
Obesity (continued). "Leptin-deficient ob/ob mice crossed with Erk1−/− mice are partially protected against hyperglycemia and hepatic steatosis despite developing severe obesity, suggesting that ERK signaling modulates insulin sensitivity independent of its potential direct effects on adipose tissue." (PMID 24209692, 2013). "Impaired hypothalamic regulation of energy balance is found in numerous genetic forms of human obesity, including congenital deficiency of leptin (MIM 164160), leptin receptor mutations (MIM 601007), MC4R melanocortin receptor mutations (MIM 601665), and Bardet-Biedl Syndrome (MIM 209900)." (PMID 23341784, 2013). "Given the role of leptin in obesity development and the association between obesity and colorectal cancer risk, Leptin (LEP) was hypothesized as a contributor to colorectal cancer." (PMID 23593308, 2013). "It is conceivable that this proinflammatory macrophage phenotype, in the context of high concentrations of serum leptin in obesity, may contribute to the pathogenesis of asthma associated with obesity." (PMID 24288549, 2013). "It led to the assumption that human obesity may also be a leptin-deficient state that could be treated with exogenous leptin administration." (PMID 22992416, 2012). "However, circulating leptin levels increase under most obesity conditions; furthermore, diet-induced obesity is associated with a reduced ability of leptin to suppress both food intake and body weight gain." (PMID 22359610, 2012). "Since tunicamycin is a synthetic and not a physiological stimulus of ER stress, continuing investigations should be extended to animal models of obesity in order to uncover to which extent ER stress- associated effects on the leptin – leptin receptor axis are of importance in-vivo." (PMID 22545089, 2012). "Leptin is an obesity-associated cytokine-like hormone encoded by the ob gene." (PMID 23028384, 2012). "An additional potential contributor to the hypophagic phenotype of our Y1Y5 receptor deficient mice is concomitant obesity, which would be expected to induce hormonal changes known to reduce food intake, such as elevated circulating concentrations of leptin and the gut satiety hormone peptide YY." (PMID 22768253, 2012). "Indeed, direct leptin action on AgRP neurons has been revealed by the obesity phenotype caused by specific deletion of LEPR in AgRP neurons." (PMID 23346045, 2012). "However, the severity of obesity observed in adiponectin deficiency is totally outweighed by that in leptin-deficient mice (ob/ob), suggesting that leptin is the master hormone of long-term weight regulation in animals." (PMID 22013516, 2012). "Moreover, short sleep was shown to be related to increased levels of ghrelin, an appetite stimulant, and decreased levels of leptin, a satiety factor, which promotes appetite and food intake thereby leading to an increased risk of obesity." (PMID 22295122, 2012). "Our results suggest that leptin may explain part of the reported association between obesity and kidney disease." (PMID 22666590, 2012). "It is unclear whether neonatal leptin regulation mediates this association between overweight mothers and offspring obesity." (PMID 22548153, 2012). "Resistance to the behavioral and biochemical effects of leptin is a hallmark of obesity." (PMID 22916190, 2012). "HFD-induced hypothalamic inflammation is suggested to be involved in the development of obesity and its associated secondary complications, with inflammation occurring centrally before systemic inflammatory markers are detected and insulin and leptin resistance are incurred." (PMID 23145019, 2012). "Because quetiapine blocks 5HT-2C, it may cause leptin resistance at the level of the hypothalamus, contributing to increased food intake and obesity." (PMID 23130910, 2012). "Our results demonstrate that serum leptin may be a useful marker of inflammation and it may be helpful in assessing the risk of obesity associated CVD." (PMID 22891684, 2012).
Obesity (continued). "We propose a model where over-reactivity of the leptin-LepRb signaling system in arcuate neurons may play causal a role in development of diet-induced obesity." (PMID 22276206, 2012). "We measured serum amylase, plasma insulin, obesity-related parameters such as leptin, cardiometabolic risk factors, and anthropometric parameters in a cross-sectional study of 54 asymptomatic subjects (mean age 48.6 ± 7.6 years) who were not being treated for diabetes." (PMID 22748134, 2012). "Leptin, a hormone produced by adipose tissue, is higher in women compared with men, which may mediate some of the sex differences in the obesity-inflammation association." (PMID 22558327, 2012). "Defects in leptin signaling lead to leptin resistance, a primary risk factor for obesity." (PMID 22359610, 2012). "With respect to abdominal fat depots, leptin deficiency-induced obesity was accompanied by a substantial increase (20-fold) in the density of mast cells in epididymal fat, while a remarkable decrease (11-fold) in the density of mast cells in inguinal (subcutaneous) fat was observed." (PMID 22313574, 2012). "This was in contrary to the suggestion of presence of genetic basis for obesity (three copies of chromosome 21) that might be a cause of more severe leptin resistance in DS." (PMID 23067442, 2012). "In wild-types, TSR induces significant transcriptional reprogramming of white adipose tissue, suggestive of increased lipogenesis, together with increased secretion of the adipokine leptin and increased food intake, hallmarks of obesity and associated leptin resistance." (PMID 23285241, 2012). "Thus, studies on leptin and obesity association to prostate cancer should differentiate patients according to androgen sensitivity." (PMID 22690216, 2012). "Studies of leptin-deficient ob/ob mice demonstrate that lack of leptin protein not only causes obesity in mice, but also results in disturbed columnar structure, decreased type X collagen expression, increased apoptosis, and premature mineralization in the growth plates." (PMID 23028384, 2012). "Furthermore, obesity has been shown to be associated with markers of systemic and vascular inflammation such as the hormone leptin." (PMID 22436173, 2012). "The association between cancer and obesity may, in part, be explained by elevated circulating leptin." (PMID 22263109, 2012). "The objective of the present study was to determine the relationship between nutritional status of zinc and vitamins A, C and E with BMI, visceral adiposity, total body fat and leptin concentrations as possible risk factors of obesity and chronic disease in women living in rural areas of Mexico." (PMID 22703731, 2012). "Thus, zinc, and vitamins A, and C are associated with obesity, adiposity and leptin concentrations in women from a rural population in Mexico." (PMID 22703731, 2012). "In our experiments, the leptin-deficient ob/ob mice were hyperphagic, consuming 50% more food compared to their controls during ad libitum conditions, and displayed significantly higher body weights characteristic of the obesity phenotype." (PMID 22448217, 2012). "To test this hypothesis, we characterized muscle SOCS3 expression in response to metabolic challenges known to be associated with insulin and/or leptin resistance such as high-fat diet feeding, genetic obesity, lipid infusion, and TNFα injection." (PMID 23115649, 2012). "Our identification of arcuate POMC neurons of DIO mice as being resistant to STAT3 phosphorylation by leptin at least opens the possibility that those specific cells might play a causal role in the development of hyperphagia and diet-induced obesity." (PMID 22276206, 2012). "Hence, obesity promotes hyperleptinemia, which in turn self promotes leptin resistance and further obesity, making leptin resistance both a consequence and cause of obesity." (PMID 23067442, 2012).
Obesity (continued). "Indeed, mice that chronically over-express leptin accumulate fat mass with age and exhibit increased susceptibility to diet-induced obesity." (PMID 22276206, 2012). "It is possible that leptin is only one of the several mediators of obesity or excess adiposity on the incidence of type 2 diabetes, so the information for type 2 diabetes risk assessment provided by assessing leptin levels is smaller than by assessing adiposity." (PMID 23251619, 2012). "This prompted the hypothesis that sleep restriction is linked with obesity via disruption of leptin and increased cravings for carbohydrate rich foods." (PMID 22844441, 2012). "However, it is plausible that ob/ob mice have elevated MCP-1 because of obesity that is a secondary response to leptin deficiency." (PMID 23216800, 2012). "Overall, increased central 5-HT1A, 5-HT1B and 5-HT6 receptor gene expression may contribute to the obesity phenotype by decreasing serotonergic tone leading to a decreased sensitivity towards satiety signals in the leptin-deficient ob/ob mice." (PMID 22448217, 2012). "The relationship observed between vitamin C and obesity in the women that participated in the study could have been caused by the effect that vitamin C has on leptin expression." (PMID 22703731, 2012). "However, genetic removal of NPY attenuated hyperphagia and obesity phenotype in leptin-deficient mice." (PMID 23346045, 2012). "Additionally, reduced adiponectin:leptin ratio associated with obesity, provides a permissive environment for tumor development." (PMID 23272114, 2012). "In obese individuals, low ZAG gene expression is associated with low serum adiponectin and high plasma leptin levels, and may play an important role in the development of obesity." (PMID 22703731, 2012). "The relationship between micronutrients and obesity might be affected by leptin, an adipokine associated with satiety." (PMID 22703731, 2012). "Zinc and vitamins A and C are associated with obesity, adiposity and leptin concentration in women from rural Mexico, and may play an important role in fat deposition." (PMID 22703731, 2012). "There is a clear association between leptin resistance and obesity." (PMID 23189059, 2012). "Leptin resistance is believed to be the primary risk factor for obesity; however, the underlying molecular mechanisms for leptin resistance remain largely unknown." (PMID 22359610, 2012). "In fact, several studies have found an association between metabolic programming of obesity and the presence of lower expression levels of leptin (and generally also insulin) receptors in the hypothalamus of these animals, as well as altered signaling of these hormones." (PMID 23189059, 2012). "Physiological acidosis may indirectly influence leptin activity through cortisol signaling in obesity which is a condition predicted to be associated with dysregulated acid-base balance." (PMID 22853725, 2012). "Leptin has been implicated in neoplastic processes, especially in obesity-related cancers, where the hormone has been shown to stimulate cancer cells growth, survival, resistance to different chemotherapeutic agents as well as migration, invasion and angiogenesis." (PMID 21771332, 2011). "The observation, that the history of CRT in ALL survivors is associated with increased plasma leptin levels suggests, that the pathogenesis of obesity may involve radiation-induced hypothalamic resistance to leptin." (PMID 21631924, 2011). "In addition, leptin, the first adipocytokine discovered, has been associated with development of obesity, as ob/ob leptin-deficient mice are markedly obese." (PMID 22027268, 2011). "In contrast, low leptin level in macrosomic babies may contribute to the weight gain, since leptin-deficient rodents and human have been shown to develop obesity." (PMID 22144985, 2011). "In addition to leptin, other obesity-related factors are linked to AD including insulin, changes to the cerebral vasculature, and direct lipotoxicity." (PMID 22013440, 2011).
Obesity (continued). "This review will focus on obesity as a risk factor for the development of neurodegenerative conditions, in particular the loss of cognitive function associated with Alzheimer's disease and other dementias, with an emphasis on the antiobesity hormone leptin." (PMID 22013440, 2011). "However, the single-leptin gene mutation only explains rare cases of human obesity; only 5% of obese patients lack leptin." (PMID 21526991, 2011). "In future studies it may be worthwhile investigating whether these miRNAs can modulate leptin resistance and hence the efficacy of leptin-associated anti-obesity drugs." (PMID 21506921, 2011). "Despite the lack of leptin mutations, leptin mRNA expression level in the adipose tissue and the serum leptin levels have been positively associated with the degree of obesity, suggesting that leptin resistance might be one of the causes for human obesity." (PMID 21526991, 2011). "Therefore, obese subjects show high leptin levels, while congenital leptin deficiency is associated with obesity." (PMID 21760816, 2011). "In humans and mice, leptin deficiency has been shown to cause obesity and diabetes." (PMID 22046310, 2011). "Obesity is associated with significant increase in serum leptin and decrease in adiponectin." (PMID 21676245, 2011). "In addition, in patients with common human obesity, brain imaging indicated that hunger associated with diet-induced obesity is related to relative leptin deficiency and is reversed by leptin reconstitution." (PMID 21853117, 2011). "Notably, administration of anthocyanine to the high fat-fed mice also altered several obesity-associated parameters including fasting blood glucose and leptin levels and enhanced β-cell function." (PMID 22254051, 2010). "Interestingly, SOCS1 has been reported to be upregulated in adipose tissue in two different models of obesity associated with leptin resistance." (PMID 20059770, 2010). "Our paper sheds light on the relation between obesity and the loss of muscle mass associated to inflammatory states suggesting that leptin treatment may be an attractive therapeutic approach to prevent muscle loss associated with inflammatory diseases." (PMID 20671928, 2010). "Leptin- or leptin-receptor-deficient mice exhibit severe obesity and diabetes." (PMID 21113299, 2010). "Loss of histamine receptor H1 (HRH1) impairs leptin control of food intake, leading to obesity." (PMID 20642857, 2010). "This defect in leptin action in obese individuals suggests that human obesity may be associated with central resistance to leptin." (PMID 20534145, 2010). "Leptin-deficient mice exhibit marked obesity, hyperphagia, insulin resistance, hypothermia and increased food efficiency, whereas iNOS knockout mice are resistant to diet-induced obesity, showing reduced epididymal fat pads and increased body temperature." (PMID 20532036, 2010). "Taken together, these data suggest that leptin may prevent the obesity-associated inflammatory state and the muscle mass loss related to inflammatory states in leptin-deficient ob/ob mice." (PMID 20671928, 2010). "Obesity is typically associated with chronically elevated leptin levels and a decreased ability of LEPRb to activate intracellular signal transduction pathways (leptin resistance)." (PMID 20059770, 2010). "Loss of AR may contribute to an increase of leptin levels and leptin resistance, which may play important roles for the development of obesity and insulin resistance." (PMID 20416077, 2010). "Since innate AHR is a common feature of leptin and leptin receptor deficient mice, as well as CPEfat mice and mice with diet induced obesity (i.e. mice with reduced and mice with increased leptin concentrations) it seems unlikely that the adipokine can act as an intermediary in the causal pathway." (PMID 21040518, 2010). "However, serum leptin was closely associated with obesity and diabetes and clearly correlated with markers of metabolism and liver function." (PMID 20871818, 2010).
Obesity (continued). "Interestingly, obesity is characterized by a systemic hyperleptinemia whereas leptin should promote weight loss through its effects on food intake and energy expenditure in the hypothalamus." (PMID 20534145, 2010). "However most obesity is associated with elevated plasma leptin levels, implying resistance to leptin's weight reducing effects." (PMID 20613882, 2010). "Central leptin resistance isconsidered to be one of the main causes of obesity." (PMID 19878575, 2009). "Furthermore, the associations of leptin with breast cancer risk remained after adjustment for obesity indices." (PMID 19223908, 2009). "In humans, mutations in the Leptin gene are a rare cause of obesity." (PMID 19772655, 2009). "We hypothesized that we would detect rare loss-of-function genetic variants similar to the link between obesity and rare variants in the leptin, leptin receptor and MC4R genes." (PMID 20016785, 2009). "It would be interesting to see whether the magnitude of those effects is similar in other models such as diet-induced obesity and diabetes (ie, non-leptin-deficient models)." (PMID 19240062, 2009). "But it has been a growing interest in determining whether polymorphic variation in or near the Leptin gene influences susceptibility to obesity in general population." (PMID 19772655, 2009). "We tested the hypothesis that rare loss-of-function ATXN2 variants cause obesity analogous to rare mutations in the leptin, leptin receptor and MC4R genes." (PMID 20016785, 2009). "Because leptin is made in adipose tissue, the baseline difference between groups is to be expected, but because leptin is a satiety factor, higher levels would seem to cause a decrease in consumption, rather than the increased caloric intake usually associated with obesity." (PMID 19671157, 2009). "It should be noted that complete lack of leptin activity is a very rare cause of severe obesity in humans, while HFD-fed mice is generally accepted as a good model for the common clinical obesity due to the combined effect of high caloric density diet and multigenic predisposition." (PMID 19865485, 2009). "We first characterized the expression of Cnr2 (encoding CB2) in the adipose tissue and in the liver, and its regulation overtime during obesity, using genetically obese leptin-deficient ob/ob mice and wild type (WT) C57Bl/6J mice fed a high fat diet (HFD) for 6 or 15 weeks." (PMID 19513120, 2009). "Obesity is often associated with increased leptin production and leptin insensitivity." (PMID 19750222, 2009). "Fat is now known to secrete humoral factors and some of these (e.g. leptin, adiponectin and resistin) can modulate insulin sensitivity; thus, the altered production of these adipokines in obesity could be involved in predisposition to diabetes." (PMID 19007436, 2008). "Insulin resistance increases plasma leptin levels, and leptin has been reported to elevate sympathetic nervous activity, suggesting that leptin-dependent sympathetic nervous activation may contribute to an obesity-associated hypertension." (PMID 18416854, 2008). "The dramatic weight reduction observed in ob/ob mice in result to leptin administration, raised expectations that human obesity might also be a leptin deficient state treatable with exogenous leptin administration." (PMID 18828917, 2008). "These leptin-deficient mice exhibit irrepressive feeding behaviour and develop a patent obesity." (PMID 18489748, 2008). "Obesity was more prominent in females in both preprohypocretin knockout mice and orexin/ataxin-3 transgenic narcoleptic mice and was associated with higher serum leptin levels, suggesting a partial leptin resistance." (PMID 18706091, 2008). "Moreover, leptin-deficient ob−/ob− obese mice exhibit insulin resistance and obesity associated to hyperinsulinemia with mitochondrial inhibition." (PMID 18335029, 2008).